CEACAM6 (CEA cell adhesion molecule 6)
Diseases named in the same sentence as CEACAM6 in open-access papers (continued):
Sharing a sentence is not in itself a finding about the gene and the disease.
colon carcinoma (27 papers, 2007 to 2025). "Previous studies have revealed that pathogenic E. coli infection induces the overexpression of CEACAM6 in colon cancer, which, in turn, facilitates pathogenic E. coli adhesion." (PMID 34938284, 2021). "Similarly, in colon cancer patients, higher levels of CEACAM6 expression was associated with higher tumor stage, and a shorter recurrence free survival." (PMID 36741860, 2023). "S. Typhimurium SL3261 was recently used to deliver genes encoding for carcinoembryonic antigen-related cell adhesion molecule 6 (CEACAM6) and 4–1BB ligand in (4–1BBL) in colon tumor-bearing mice." (PMID 38116133, 2023). "Downregulation of CEACAM6 increased E-Cadherin levels in colon cancer cell lines, suggesting that CEACAM6 is a factor directly responsible for these cells’ invasive properties." (PMID 36741860, 2023). "The expression of CEACAM5 and CEACAM6 in colon cancer cell lines is increased in the presence of proinflammatory cytokine interleukin 6, supporting an important role in inflammation in colorectal cancer." (PMID 36741860, 2023). "The human CEA (also named CEACAM5) and CEACAM6 have also been shown to be strongly positive in most colon cancers." (PMID 32064046, 2020). "CEACAM1, CEACAM5 and CEACAM6 have been demonstrated to be over-expressed in certain epithelial cancers, such as colon cancer." (PMID 32064046, 2020). "In particular, microfluidic perfusion stimulates expression of genes coding glycoproteins CEACAM5 and CEACAM6, prototype biomarkers for colon carcinoma." (PMID 30836980, 2019). "In colon cancer, CEACAM6 overexpression prevents colonocyte differentiation and promotes oncogenesis in nude mice." (PMID 29137373, 2017). "Its family member CEACAM6 is also upregulated in adenomas and carcinomas of the colon and an independent predictor of poor survival." (PMID 26673628, 2015). "coli strains can induce the expression of CEACAM6 in intestinal epithelial cells, and yet CEACAM6 is a human tumor maker, whose overexpression has been observed in colonic tumors." (PMID 23457644, 2013). "Our results differ from those in a recent publication on the blockage of Ad5 trafficking in colon cancer cells by CEACAM6." (PMID 21455297, 2011). "In half of the matched cases (N = 6), CEACAM6 expression was much greater in the liver metastasis than in the primary colon tumors, and in the remaining 6 cases, the amounts were comparable between the primary and the metastatic liver sites." (PMID 17201906, 2007). "The amount of CEACAM6 in metastatic colon tumors found in liver was higher than in many primary colon tumors." (PMID 17201906, 2007). "CEACAM6 is a human tumor marker found in excess in colon tumors." (PMID 35899040, 2022). "CEACAM6 was highly upregulated in colon cancer tissues and may therefore be a suitable candidate for a diagnostic marker of colorectal cancer." (PMID 33483567, 2021). "CEACAM1, CEACAM5 and CEACAM6 are co-expressed in epithelial cells of the gastro-intestinal tract and can also be over-expressed in endometrial, lung, ovarian, cervical, breast and colon cancers." (PMID 32064046, 2020). "Additionally, we evaluated the effect of pHLIP-siCEACAM6 in two CEACAM6-epxressing colon cancer cell lines, HT29 and LoVo." (PMID 31474761, 2019). "Studies have shown that CEA and CEACAM6 levels are elevated in colon cancer patients." (PMID 27100181, 2016). "CEA and CEACAM6 are considered to be pro-tumorigenic in colon cancer." (PMID 27100181, 2016). "Moreover, the level of CEACAM6 in liver metastases of colon cancers was higher than in many corresponding primary tumors." (PMID 25427744, 2015). "To date, pancreatic and colonic cancer have been the focus of CEACAM6 expression in the literature." (PMID 17201906, 2007). "In colonic cancer, CEACAM6 may play an important role in the development of distant metastases." (PMID 17201906, 2007).
colon carcinoma (continued). "METTL13 knockdown also downregulated CEACAM6, which regulates tumor proliferation and migration through ERK-MAPK and PI3K-AKT signaling in several cancers, including lung and colon cancer." (PMID 41282185, 2025). "Similarly, a broad reduction in cell adhesion markers including CEACAM1, CEACAM5, CEACAM6, and CEACAM7 occurs in human colon cancer cell lines after treatment with chloroquine." (PMID 39900438, 2025). "In contrast to the higher expression off CEACAM6 in many secondary liver sites from colon cancer, there was no pattern for CEACAM6 expression between primary tumor and lymph node metastases." (PMID 17201906, 2007).
gastric cancer (25 papers, 2013 to 2026). A primary or metastatic malignant neoplasm involving the stomach. "In a study of gastric cancer patients, it was noted that an increased level of CEACAM6 DNA in the peripheral blood was significantly associated with a higher stage of the disease as well as lymph node metastasis." (PMID 36741860, 2023). "Analysis of tumor specimens of gastric carcinoma patients using immunohistochemistry revealed increased CEACAM6 protein levels were associated with a higher stage, and that high CEACAM6 protein levels were associated with a shorter recurrence free survival." (PMID 36741860, 2023). "CEACAM6 is overexpressed in colorectal and gastric cancers and is associated with the adhesion and invasion of tumor cells." (PMID 36341379, 2022). "In gastric cancer, it has been discovered that up-regulation of circ_0008035 can regulate the expression of CEACAM6 by sponging miR-1256, thereby promoting the growth of gastric cancer." (PMID 38796667, 2024). "When we assessed the expression status of individual gastric cancer oncogenes (e.g., CEACAM6, EGFR, MET, CCND1, and KRAS) among the tumor epithelial clusters, the EpiInt1 tumor epithelial cluster exhibited the largest increase." (PMID 34642171, 2022). "Data mining results show that CEACAM6 is overexpressed in gastric cancer and is correlated with lymph node metastasis." (PMID 29137373, 2017). "Interesting, CEACAM6 is also positively correlated with lymph node metastasis of gastric cancer (p=0.0134, Right)." (PMID 29137373, 2017). "This gene can be an important downstream effector of CEACAM6 and mediating gastric cancer progression." (PMID 29137373, 2017). "These hub genes such as SRC (Proto-Oncogene C-Src), DNM1L (Dynamin 1-Like) and POLR1C (polymerase (RNA) I polypeptide C) are critical downstream effectors of CEACAM6 in gastric cancer progression." (PMID 29137373, 2017). "To elucidate the potential roles CEACAM6 play in gastric cancer development and progression, we obtained downstream gene signatures of CEACAM6 from LINCs database." (PMID 29137373, 2017). "Results in previous sections show that CEACAM6 over expressed in gastric cancer samples and positively correlated with gastric cancer progression." (PMID 29137373, 2017). "The rate of samples positive for CEACAM6 was 62.9% (78/124) in gastric carcinoma specimens with poorly differentiated tumors, which was higher than that with well to moderately differentiated tumors (35.3%, 24/68, p < 0.001)." (PMID 29137373, 2017). "The proportion of CEACAM6 positive specimens was 51.4% (224/436) in the gastric carcinoma specimens and yellow-brown CEACAM6 granules were observed mainly in the cytoplasm." (PMID 29137373, 2017). "Together, these results suggest that CEACAM6 upregulation is a cell surface response to H. pylori CagA, and is retained in early gastric cancers." (PMID 27421133, 2016). "They highlight a novel link between CEACAM6 expression and CagA in gastric cancer, and suggest CEACAM6 to be a promising biomarker to aid with the fluorescent endoscopic diagnosis of early neoplastic lesions in the stomach." (PMID 27421133, 2016). "Together, these results suggest that a fluorescently labelled CEACAM6 antibody can directly bind to live gastric cancer tissue and therefore have applicability in the context of endoscopic diagnosis of early gastric cancer." (PMID 27421133, 2016). "The results show a potential clinical utility of a fluorescently conjugated CEACAM6 antibody for the endoscopic diagnosis of early gastric cancer." (PMID 27421133, 2016). "Together, these data suggest that CEACAM6 mRNA is upregulated by the presence of H. pylori CagA, and is retained in advanced gastric cancers." (PMID 27421133, 2016). "We show that the cell surface protein CEACAM6 is upregulated by the H. pylori CagA oncoprotein, and highly expressed on early gastric cancers as well as premalignant lesions." (PMID 27421133, 2016).
gastric cancer (continued). "Consistent with earlier reports, a significant increase in CEACAM6 immunostaining for gastric cancer in comparison to adjacent normal tissue was noted, p < 0.001." (PMID 27421133, 2016). "Accordingly, this platform was used to confirm the overexpression of CEACAM6 protein in a tissue microarray of advanced gastric cancer with matched normal tissue (n=29)." (PMID 27421133, 2016). "Here the results of this 2-step screening approach are reported, highlighting the identification of CEACAM6 as a potential endoscopic biomarker of early gastric cancer." (PMID 27421133, 2016). "CEACAM6 staining provided an AUC of 0.831 in an ROC analysis for the distinction of normal mucosa from early gastric cancer." (PMID 27421133, 2016). "We used quantitative digital immunohistochemistry to measure CEACAM6 protein levels in tissue microarrays of gastric cancer." (PMID 27421133, 2016). "The high expression of CEACAM6 transcripts in gastric cancer was confirmed using other publicly available datasets of gastric cancer gene expression." (PMID 27421133, 2016). "We observed a clear increase in the mean staining intensity for CEACAM6 in early gastric cancers (T1N0M0 and T1N1M0) when compared to adjacent normal tissue, p < 0.001." (PMID 27421133, 2016). "We demonstrate an increase in CEACAM6 in early gastric cancers, when compared to matched normal tissue, with an AUC of 0.83 for diagnostic validity." (PMID 27421133, 2016). "We show that a fluorescently conjugated antibody to CEACAM6 is able to bind to gastric cancer samples from xenografts, and be visualized by a confocal laser endomicroscopy (CLE) probe that is compatible with most commercially available endoscopy equipment." (PMID 27421133, 2016). "Among the transcripts enriched upon CagA induction in vitro, a significant elevation of CEACAM6 was noted in gene expression datasets of gastric cancer." (PMID 27421133, 2016). "A fluorescently tagged antibody to CEACAM6 avidly binds to gastric cancer tissue and can be visualized by commercially available endoscopic methods." (PMID 27421133, 2016). "CEACAM6 was chosen for further analysis on the basis of its increased levels in gastric cancer over normal tissue (8-fold in the SGCC data set)." (PMID 27421133, 2016). "As a proof of concept for the potential utility of CEACAM6, we aimed to evaluate the ability of a conjugated anti-CEACAM6 reagent to directly bind gastric cancer tissue." (PMID 27421133, 2016). "Taken together, these findings suggest that CEACAM6 is a potentially useful marker for gastric cancer and differentiates between carcinomas and gastric dysplasia." (PMID 25427744, 2015). "We observed differential expression of the AP11-reactive CEACAM6 epitope in invasive gastric cancer and dysplastic lesions." (PMID 25427744, 2015). "They found higher CEACAM6 transcript levels in gastric cancer tissues compared to adjacent normal tissues, and CEACAM6 transcripts were detectable in 92 % (11/12) and 25 % (3/12) of gastric cancer and normal gastric mucosa samples, respectively." (PMID 25427744, 2015). "Roy et al5 suggested that CEACAM6 was a biomarker for gastric cancer." (PMID 37089051, 2023). "Levels of CEACAM6 DNA detected by RT-PCR in peripheral blood cells of gastric cancer pts." (PMID 30809317, 2019). "In gastric cancer, CEACAM6 was proposed as a prognostic biomarker and potential therapeutic target." (PMID 30809317, 2019). "A study from the same group showed that CEACAM6 could promote gastric cancer invasion and metastasis by inducing Epithelial-mesenchymal transition." (PMID 29137373, 2017). "Since CEACAM6 has critical implications in gastric cancer development and metastasis, we searched LINCs database for available drugs that could down regulated CEACAM6 expression." (PMID 29137373, 2017). "The application of Tamoxifen in combination with traditional chemotherapeutics in the treatment for CEACAM6 over expression gastric cancer patients may generate positive benefits." (PMID 29137373, 2017).
gastric cancer (continued). "Recently, a study by Roy and co-authors indicated that CEACAM6 could be upregulated by Helicobacter pylori CagA and was a biomarker for early gastric cancer." (PMID 29137373, 2017). "The proportion of CEACAM6 positive patients is 51.4% (224/436) in the gastric carcinoma specimens." (PMID 29137373, 2017). "The high levels of discrimination demonstrated by the AUC of CEACAM6 in early gastric cancer and intestinal metaplasia specimen suggest a rationale for the further development of this reagent as a tool for early gastric cancer diagnosis, in conjunction with advances in fluorescent endoscopy." (PMID 27421133, 2016). "CEACAM6 has previously been reported to be upregulated in a variety of cancers, including gastric cancer but its biological role remains unclear." (PMID 27421133, 2016). "Together, these findings suggest that CEACAM6 may be useful as a surface marker of early gastric cancer and pre-neoplastic lesions." (PMID 27421133, 2016). "Finally, we show that a fluorescently conjugated CEACAM6 antibody binds avidly to freshly resected gastric cancer xenograft samples and can be detected by endoscopy in real time." (PMID 27421133, 2016). "Here, we aimed to investigate the role of CEACAM6 expression in predicting the overall survival (OS) in gastric cancer (GC)." (PMID 28883649, 2017). "This study aims to investigate the prognostic power of carcinoembryonic antigen-related cell adhesion molecule 6 (CEACAM6) in gastric cancer (GC) and its potential role in cancer development and progression." (PMID 29137373, 2017). "Furthermore, we found several available drugs that could inhibit the expression of CEACAM6, which in turn may lead to the repression of gastric cancer progression." (PMID 29137373, 2017). "As CEACAM6 levels increase in response to H. pylori CagA (an early event in carcinogenesis) and are retained in advanced cancers, we hypothesized that it may be a marker of early gastric cancer." (PMID 27421133, 2016). "We recently reported that CEACAM6 expression is upregulated in Gastric cancer (GC) tissues and promoted GC metastasis." (PMID 25398131, 2014). "Among the hits identified in the CagA screen, 4 of them (MMP1, CEACAM6, ITGA2, C3) showed at least 2-fold increases in gastric cancer when compared to normal controls." (PMID 27421133, 2016). "What’s more, our team has been worked on some of the differential genes such as PHF10, CEACAM6, SFRP1, SOX11, CLDN1 to investigate their expression and functions in gastric cancer and the results perfect proved our microarray data." (PMID 25928635, 2015). "Four of these five integrations into STAD are in genes known to be up-regulated in gastric cancer, specifically CEACAM5, CEACAM6, TMSB, and CD74." (PMID 23840181, 2013). "However, in gastric cancer cells, Smad3-mediated TGF-β signaling induces carcinoembryonic antigen (CEA)-related cell adhesion molecule 6 (CEACAM6) expression and promotes EMT in gastric cancer cells." (PMID 38818471, 2024). "Furthermore, among overexpressed genes in both gastric cancer types, we found CEACAM1 and CEACAM6, two recognized markers of angiogenesis, invasion and metastasis in gastric cancer." (PMID 34012923, 2021). "The binding partners of CEACAM6 are not well characterized, but it has been described to promote in vivo metastasis, tumor angiogenesis, vasculogenic mimicry in gastric cancer, and confers a poor prognosis to cancers overexpressing the protein." (PMID 27421133, 2016). "Evaluation of CEACAM6 transcript levels using RNA-seq data of matched tumor and adjacent normal tissue, from the SGCC (n=15) and TCGA (n=29) also confirmed a significant enrichment of the transcript in gastric cancer." (PMID 27421133, 2016). "We observed high expression (86 %) in gastric cancer, which is consistent with previous reports, but no or low CEACAM6 expression in dysplasia." (PMID 25427744, 2015).